IL6 (interleukin 6)
Diseases named in the same sentence as IL6 in open-access papers (continued):
Sharing a sentence is not in itself a finding about the gene and the disease.
tumor (continued). "However, we found that several prominent angiogenic factors such as VEGF-A, PDGF-A, and IL-6 in the metastatic tumor cells were not inhibited, while all these factors were significantly inhibited by IFN-α in the primary tumor site." (PMID 23527047, 2013). "Also Listeriaat-Mage-b reduced IL-6 levels in the primary tumors (tumor cell lysates), but not in MDSC in blood and primary tumors." (PMID 24156030, 2013). "Interestingly, pharmacologic blockade of IDO leads to enhanced IL-6 production by pDC that converts tolerogenic CD4+ Tregs into TH17-like cells, and this conversion correlates with enhanced CD8+ T cell activation and anti-tumor immunity." (PMID 23874338, 2013). "Therefore, we examined the correlation between IL-6 and MDSC recruitment after irradiation by analyzing MDSC levels in tumor-bearing mice 48 h after irradiation, with or without IL-6-silencing vectors." (PMID 23806095, 2013). "Moreover, Listeriaat-Mage-b significantly increased the production of IL-6 in sub populations of the MDSC (with an exception of gMDSC in tumors), probably to protect themselves from immune clearance, but curcumin strongly reduced the IL-6 production in both types of MDSC in blood and primary tumor." (PMID 24156030, 2013). "However, in endocrine treated J110 tumours, there was no consistent increase in IL6 RNA, although there was a trend in the fulvestrant group." (PMID 23868506, 2013). "By contrast, the over-expressed genes in the networks may trigger tumorigenesis of HNSCC by altering gene expression associated with inflammatory, proliferation, apoptosis and other processes, such as IL6, IGFBP3, ELF3, and PTGES in the both subgroups of tumor cells." (PMID 24069219, 2013). "To study the effects of pardaxin on tumor functions, we performed a real-time RT-PCR analysis of caspase-3, caspase-7, caspase-8, caspase-9, Bax, Bcl-2, STAT2, ATF3, STAT3, SOCS3, IL-2, cathelicidin, TNF-α, MyD88, NF-κB1, p65, IFN-β1, IFN-γ, IL-1β, IL-6, IL-7r, and IL-10." (PMID 23015777, 2012). "In addition, the IHC staining method does not allow detection of serum or saliva IL6 levels, so IHC was used as a semi-quantitative method to detect the protein levels in the tumor cells." (PMID 23185547, 2012). "Furthermore, based on stimulation with conditioned media we have shown that IL-6 is mainly induced in the osteoblasts rather than in the MDA-MB-31 tumor cells." (PMID 22235336, 2012). "The lower serum albumin concentration in advanced cancer patients may be due to the release of some cytokines such as interleukin 6 or TNF, to suppression of hepatocyte production of albumin, or to increased capillary permeability to albumin by the tumor or its surrounding tissues." (PMID 22559838, 2012). "Recent studies have demonstrated that LLC cells-produced factors such as versican is necessary for tumor growth and metastasis, a process that depends on TLR2-mediated myeloid cell activation, where activation of NF-κB results in inflammatory factors TNFα, IL-6 production." (PMID 23284890, 2012). "However, when the concentration of IL-6 was low, such as 10 ng/mL, the CXCL7 production was higher than that in tumor cells without any IL-6 treatment." (PMID 23136963, 2012). "Recent studies have shown that DNA methylation, IL-6, bone morphogenic protein, prostaglandin E (PGE)/EP4, glucocorticoid, and non-steroidal anti-inflammatory drugs could regulate S100P expression during tumor progression." (PMID 23216986, 2012). "However, SE and EE tumor-bearing mice showed significant increases in IL-6, TNF-α, MCP-1 and PAI-1 compared to SE and EE non-tumor-bearing mice." (PMID 23272114, 2012). "Notably, all the mice injected with IL-6-knocked-down cells showed no tumor mass formation at all in the fatpads up to 45 days after tumor inoculation." (PMID 21967801, 2011).
tumor (continued). "Given that expression of IL-6, IL-8, MMP2, and VEGF increased in parallel with STAT3 and AKT activation in HCC cells treated with IL-17, STAT3, and AKT signaling may play important roles in inducing these proinvasive factors and hence tumor progression." (PMID 22171994, 2011). "As transglutaminase 2 (TG2), which has been associated with inflammatory signaling, has been suggested to play a role in tumor behavior, we propose that TG2 may be an important linker inducing interleukin (IL)-6-mediated cancer-cell aggressiveness, including distant hematogenous metastasis." (PMID 21967801, 2011). "However, non-lethal PDT can also stimulate tumor growth-promoting autocrine loops, as seen by the upregulation of IL6 and its receptor." (PMID 21738796, 2011). "We have previously identified IL-1α to be the main tool used by the tumor cells to activate CAFs to produce several inflammatory factors (e.g., IL-6, CCL20, CXCL8, COX-2, and VEGF-A), and this could be one mechanism the tumor cells use to escape elimination by the immune system." (PMID 22190968, 2011). "However, neither the basal secretion of IL-6 nor the induced secretion of IL-6 by PGE2 in fibroblasts correlated with fibroblast tumor promoting ability in vivo or their ability to expand CD44+/CD24−/EpCAM+ cells in vitro." (PMID 21957456, 2011). "Importantly, pharmacological inhibition of ERK in C26 carcinoma-bearing mice markedly attenuates muscle depletion and improves muscle function, without modifying tumor growth or IL-6 circulating levels." (PMID 21048967, 2010). "Cytokines secreted by the activated tumor stroma modulate tumor growth and regulate their survival and invasiveness through activation of oncogenic signaling pathways in tumor cells, examples being activation of NF-κB by TNFα and IL-1β, and activation of STAT3 by IL-6." (PMID 20661477, 2010). "Additionally, human MSC but not murine MSC stimulated tumor growth primarily through the paracrine production of secreted IL6." (PMID 19352430, 2009). "Moreover, we could show that IL-6 and TGF-β1 is produced in the tumour tissues of most NSCLC patients to variable degree." (PMID 18682839, 2008). "Among these candidate cytokines, IL-6, which activates Stat3 through the gp130/Jak pathway, is notable for its pleitrophic tumor-promoting activities, including anti-apoptotic, pro-invasive, and immune-stimulatory effects attributable to the activation of Stat3 target genes." (PMID 17531096, 2007). "In order to explore whether adipose tissue-derived cytokines and lipid mobilising factor are involved in MAC16-induced lipoatrophy, gene expression of TNFα, IL-6 and zinc-α2-glycoprotein (ZAG) known as a lipid-mobilising factor, in white fat was determined in tumour-bearing and freely fed animals." (PMID 17047651, 2006). "Immunohistochemistry suggested the source of IL-6 to be tumour cells rather than host cells." (PMID 17088911, 2006). "This would be consistent with the observations in the present study that circulating interleukin-6 and interleukin-10 concentrations were not strongly correlated with tumour volume but were similarly correlated with each other before and after resection of the renal tumour." (PMID 17003778, 2006). "Histological studies of bone metastases show that tumour cells remain in the bone marrow cavity and secrete factors that regulate bone cells including parathyroid hormone related protein (PTHrP), tumour necrosis factor (TNF), interleukin-6 (IL-6) and transforming growth factor (TGF)β." (PMID 16880790, 2006). "However, in the present study, when the analysis was confined to those patients with stage I disease, neither C-reactive protein, interleukin-6 or interleukin-10 appeared to normalise on resection of the primary tumour." (PMID 17003778, 2006). "Furthermore, they suggest that interleukin-6 is produced primarily by the host rather than the tumour." (PMID 15505624, 2004).
tumor (continued). "This increase could be related to tumour-derived factors that may either promote the mobilisation of CD34+ cells from the bone marrow, such as GM-CSF, or inhibit DC maturation from CD34+ precursors, such as VEGF, M-CSF and IL-6." (PMID 14562018, 2003). "Moreover, intramuscular injections of MPA (100 mg kg−1 twice a week) into nude mice bearing KPL-4 transplanted tumours significantly decreased serum IL-6 levels without affecting tumour growth and preserved the bodyweight of recipient mice." (PMID 10027341, 1999). "Moreover, by inhibiting pro-inflammatory cytokines like IL-6 and TNF-α in the TME, AE can mitigate chronic, tumor promoting inflammation and modulate the activities of other immune cells, including T cells and dendritic cells, thus establishing a microenvironment detrimental to tumor proliferation." (PMID 41601956, 2026). "Also, the use of biomarkers (e.g. IL-6) may lead to more targeted treatments of irAEs, minimizing adverse effects without compromising the anti-tumor efficacy of ICIs." (PMID 40181971, 2025). "In addition, IL6 is also crucial for the progression and metastasis of HCC through the activation of Janus kinase-1 (JAK1) and its downstream signal transducer and activator of transcription (STAT), which directly stimulate the proliferation, migration, and invasion of tumor cells." (PMID 39744421, 2025). "Furthermore, the relationship between M1-like macrophages and tumor metastasis may be partially attributed to the influence of inflammatory cytokines, such as IL-1β, TNF-α, and IL-6, which can directly or indirectly promote the proliferation of endothelial cells." (PMID 40438141, 2025). "Additionally, SCs co-cultured with tumor cells can secrete high levels of IL-6, which promotes the migration and invasion of the cancer cells through the activation of STAT-3 signaling, however, it can be mitigated by neutralizing IL-6 or inhibiting STAT-3 expression." (PMID 40567365, 2025). "Similarly, IL-6 knockout in KPC mice delayed tumor progression without impacting ADM formation." (PMID 40619414, 2025). "In addition, direct targeting of cytokines such as IL-6, which is already being targeted clinically with agents like tocilizumab, could potentially be explored in combination with BET inhibitor to further suppress tumor-promoting inflammation." (PMID 41583469, 2025). "Additionally, while tumor cells contain immune suppressive molecules such as TGF-beta, soluble HLA-G, and IL-10, intra alia, senescent cell lysates contain molecules that may actually stimulate immunity through dendritic cell maturation such as interleukin-6." (PMID 41316207, 2025). "Furthermore, elevated IL-6 expression is positively correlated with PCP tumor invasion into the hypothalamus, suggesting that these inflammatory mediators could serve as potential therapeutic targets to prevent tumor invasion." (PMID 40433410, 2025). "In the AOM/DSS-induced murine CAC model, Th17-related cytokines, including IL-17A, IL-21, IL-22, TNF-α, and IL-6, are produced by tumor-infiltrating lymphocytes (TIL), which could activate the STAT3/NF-κB pathway, thereby promoting CAC cell proliferation and accelerating tumor progression." (PMID 40109347, 2025). "In addition, IL-6 interacts with both epidermal growth factor receptor (EGFR) to promote immunosuppressive microenvironment by inducing myeloid-derived suppressor cells (MDSC) and the vascular endothelial growth factor receptor (VEGFR) to drive tumor-induced angiogenesis in EC." (PMID 40519900, 2025). "Although serum biomarkers like AFP, CD147, and IL-6 may be biologically correlated (e.g., inflammation and tumor progression pathways), the VIF test confirmed no severe multicollinearity (all VIF < 10), suggesting their independent contributions to the nomogram are statistically valid." (PMID 40919145, 2025).
tumor (continued). "Notably, GSDMD knockout did not completely inhibit the production of IL-6, tumor TNF-α, and IL-10, suggesting that GSDMD-independent pathways may contribute to inflammation." (PMID 41345109, 2025). "In lung cancer, inhibiting NINJ1 significantly increased the expression and secretion of IL-6, enhanced cell migration, and ultimately induced a significant increase in the incidence of lung metastasis, as well as the sizes and number of tumor nodules, without affecting tumor growth." (PMID 39958360, 2025). "Thus, targeting IL-6 in MPM may simultaneously mitigate irAEs and suppress tumor progression." (PMID 41244903, 2025). "Consequently, the role of IL-6 as a pro-inflammatory cytokine in tumor immunity may not be as deleterious in tumor promotion as conventionally perceived." (PMID 40426998, 2025). "Furthermore, the secretion of pro‐inflammatory cytokines, including IFN‐γ, TNF‐α, and IL‐6, was attenuated in irradiated 4T1 cells co‐culture supernatants relative to non‐irradiated 4T1 cells co‐culture, potentially due to the RT‐induced promotion of TGF‐β secretion by tumor cells." (PMID 40470716, 2025). "In addition, examining other tumor types will help determine whether PRKCSH effects are context-dependent, and further studies are needed to delineate how PRKCSH regulates cytokine secretion, particularly IL-6 and IL-8." (PMID 41350724, 2025). "Additionally, Interleukin-6 (IL-6), the levels of which were high in HIV-1 infected patients (P < 0.001) compared to non-HIV-infected individuals, was significantly higher in advanced cases of tumors (P < 0.001), and IL-6 level was correlated with Vpr in the non-tumor group (P = 0.010)." (PMID 38166062, 2024). "However, the relationship between precise radical RT and IL-6 concentration in confined HCC without a tumor thrombus remains unknown, as there are few reports on this topic." (PMID 39619013, 2024). "In addition, increased mRNA levels of IL‐6 and IL‐10, as well as increased expression of PD‐L1, were observed in BMDMs cocultured with LLC‐shCx43 cells compared with LLC cells, indicating that knocking down Cx43 in tumour cells induced macrophages towards the protumor type." (PMID 39592436, 2024). "Thus, IL-6/IL-6R may suppress cell proliferation of CRC cells, especially in tumor buds." (PMID 38486225, 2024). "Importantly, such therapy does not appear to interfere with anti-tumor immune effector responses, raising the possibility that localized therapy directed against the IL-6 axis could counter EMT while unleashing a preexisting, but silenced local anti-tumor response." (PMID 39114667, 2024). "Interestingly, tumor location, alcohol consumption, BMI and patients’ physical activity, as well as socio-economic indicators, such as education and financial situation, did not have a significant correlation with serum IL-6 concentrations." (PMID 38396821, 2024). "The related mechanisms may involve an inhibitory effect on the IL-6/LIF system, promoting the release of ligands of the CXCR3 receptor, chemokines CXCL9 and CXCL10 (IP-9), which chemoattract several types of immune cells that infiltrate a tumor and prevent its growth." (PMID 38891915, 2024). "However, rather than a focus on neovascularization, this study focused on how IL6 and NOTCH signaling cooperate to promote cancer cell stemness, suggesting yet another possible intersectional mechanism by which IDO1 contributes to fostering a tumor-promoting inflammatory TME." (PMID 37182174, 2023). "Moreover, inflammatory cytokines secreted by the tumor, such as TGF-β, TNF-α, IL-1, IL-6, IL-8, and IL-10, could induce local inflammation and fibrosis, which affect the electrophysiological characteristics of adjacent myocardium of pulmonary veins and atrium, facilitating occurrence of AF." (PMID 37519821, 2023).
tumor (continued). "Because our results suggested that the IL-6 classical signaling, but not trans-signaling, may be related to the anti-tumor immune responses in NSCLC patients treated with ICIs, anti-IL-6 or anti-IL-6R Abs, but not sgp130 fusion proteins, may be promising to improve the efficacy of ICIs." (PMID 38469154, 2023). "Therefore, inflammation mediated by IL-6–Th17 pathway can probably drive the progress of irEC, so that addition of IL-6 blockers to tumor-bearing mice treated with anti–CTLA-4 reduces Th17, macrophages counts and tumor load, but promotes tumor shrinkage and increases survival rate of mice." (PMID 37404814, 2023). "CAR-M recruited CD3 T cells and reduced PD-L1+ cells at the tumor site—confirming that the engineered Mφ was not the only driver of the anti-tumor response—and increased serum levels of the inflammatory cytokines IL-1β, IL-6, and TNF-α, demonstrating a systemic immune response." (PMID 38139461, 2023). "In addition, increased expression of tumor-related inflammatory mediators and cytokines, such as TNF-α, IL-1, and IL-6 may stimulate the bone marrow to release neutrophils, resulting in an increase in the circulating neutrophil count and decrease in the circulating lymphocytopenia." (PMID 36899319, 2023). "In addition, GPER has also been reported to inhibit inflammation, tumor cell migration, and tumor angiogenesis through reducing phosphorylation, nuclear localization, and the transcriptional activity of NF-κB, and TNF-α- or lipopolysaccharide-induced IL-6 secretion." (PMID 37759810, 2023). "Furthermore, HDAC3LCKO&IL-6−/− female mice developed more and larger tumours than HDAC3LCKO female mice, implying that HDAC3 deletion may amplify the negative effects of IL-6 deficiency." (PMID 37752418, 2023). "Notably, IL-6 and IL-8 are crucial for epithelial–mesenchymal transition (EMT) via activation of the protein kinase activated by the mitogen (MAPK) pathway, with these key processes promoting cell motility, wound healing, tissue regeneration, fibrogenesis, and tumour metastasis." (PMID 37047238, 2023). "Therefore, L.E.M. extract not only directly activates DCs but also contributes to the induction of anti-tumor responses through a complex mechanism of maintaining dendritic cell function by suppressing the production of immunosuppressive cytokines such as TGF-β and IL-6." (PMID 37553633, 2023). "There is a number of clinically registered anti-IL6 and anti-IL6R antibodies that could potentially be exploited in this area; however, caution should be exerted with immune therapies until a better understanding of the biology of these tumours and responses to treatment are known." (PMID 37419892, 2023). "For example, tumor-derived exosomes could transfer prostaglandin E2 (PGE2) and TGF-β to induce the accumulation of myeloid-derived suppressor cells (MDSCs) expressing cyclooxygenase-2 (COX-2), interleukin 6 (IL-6), vascular endothelial growth factor (VEGF) and arginase-1." (PMID 36594094, 2023). "In particular, oestrogens may favour an immunosuppressive TME by enhancing Th2 responses, tumour-promoting cytokines (IL-4, IL-6, IL-17A and TNF) and M2 TAM infiltrations, unlike M1 TAM infiltration and Th1 responses, which are commonly joined with Th1 cytokines (IL-12 and IFN)." (PMID 38332913, 2023). "Additionally, Interleukin 6 (IL-6) and tumor necrosis factor-α (TNF α), which are elevated in metastatic breast cancer patients, have been shown to induce the binding of MDA-MB-231 tumor spheroids to E-selectin coated microtube surfaces compared to single cells that failed to achieve such binding." (PMID 37442876, 2023). "Thus, STAT3/IL-6 signaling may involve gankyrin-regulated crosstalk between tumor cells and nonparenchymal cells." (PMID 36660927, 2023). "Thus, elevated IL-6 may be a negative prognostic marker because it is reflecting the presence of a more advanced or aggressive tumor." (PMID 38022653, 2023).